CD36 (CD36 molecule (CD36 blood group))
Diseases named in the same sentence as CD36 in open-access papers (continued):
Sharing a sentence is not in itself a finding about the gene and the disease.
ovarian carcinoma (continued). "Therefore, inhibition of CD36 can effectively inhibit ovarian cancer metastasis." (PMID 33926551, 2021). "Based on the coordinated expression of TSP-1 and CD36 during ovarian follicle development, and the results from our work in the ovarian cancer model, we hypothesized that CD36 is an important mediator in the regulation of ovarian cell function and folliculogenesis." (PMID 24628875, 2014). "The authors of this study demonstrated that the prosaposin-based therapeutic agent inhibits the progression of ovarian cancer through TSP-1 and downstream CD36 signaling, which further highlights the importance of CD36 in the tumor microenvironment." (PMID 38370376, 2024). "In the expansion phase, subjects were enrolled into one of the five cohorts: recurrent glioblastoma (rGBM), pancreatic cancer, ovarian cancer, TNBC, and a high-CD36 and high-CD47 basket cohort." (PMID 39627379, 2024). "There were also indications in which the CD36/CD47 expression levels were consistent across all stages, such as Cervical cancer and Ovarian cancer." (PMID 39627379, 2024). "In ovarian cancer, binding of the TSP-1 three type 1 repeats (3TSR) domain of TSP-1 to GPIV (CD36) normalizes the tumor vasculature and exhibits antitumor function." (PMID 36831623, 2023). "Their findings showed ovarian cancer cells cocultured with adipocytes had elevated CD36 and FABP4 expression, whereas knockout of FABP4 resulted in inhibition of several tumorigenic pathways including proliferative and migration in ovarian cancer cells." (PMID 36428985, 2022). "Similarly, in ovarian cancer, PSAP-derived peptides inhibit tumor growth and metastasis via TSP-1/CD36 signaling." (PMID 40801564, 2025). "Therefore, in ovarian cancer’s lipid-rich microenvironment, M2 polarization is driven by PUFA metabolites, CD36/FABP4-mediated FA uptake, PPARγ activation, and cholesterol efflux via ABC transporters." (PMID 40709184, 2025). "To elucidate the downstream effects of blocking endothelial CD36-mediated CD5L signaling, we obtained an endothelial-specific CD36flox/flox knockout mouse model CD36ffTie2Cre and inoculated the mice with syngeneic murine ovarian cancer ID8-Luc cells." (PMID 37100807, 2023). "Notably, targeting CD36 with function-blocking antibodies or genetic ablation reduced the tumor burden and metastasis in OSCC, gastric, and ovarian cancer xenograft mouse models, with reductions of up to 90% observed in the size of lymph node metastases." (PMID 37371076, 2023). "A body of knowledge and evidence has been collected for CD36, indicating a critical role in many entities, as CRC, gastric, cervical or ovarian cancer, impacting an array of signaling pathways, but the overall conclusion concerning the role of CD36 remains inconsistent." (PMID 35323656, 2022). "Indeed, fatty acid transporters, such as CD36 or fatty acid transporter protein (FATP), help tumor progression in oral squamous cell carcinoma, ovarian cancer and melanoma, by increasing fatty acid uptake." (PMID 33499022, 2021). "Last, but not least, CD36 shows a higher concentration and is more prominent in peritoneal metastases of ovarian cancer than in primary ovarian cancer and normal tissue." (PMID 33809784, 2021). "There is no proof yet of the involvement of CD36 in ovarian cancer development and progression." (PMID 38370376, 2024). "Omental adipocytes co-cultured with ovarian cancer cells showed that apelin secreted from omental adipocytes activates the apelin/APL receptor (APJ) pathway, and further promotes ovarian cancer metastasis through the upregulation of CD36 by the APJ-STAT3 signaling pathway." (PMID 39125923, 2024). "Our study showed that a blockade of CD36, a fatty acid transporter known to drive FAO37, did not affect FAO in the presence of COL11A1, suggesting that CD36-mediated fatty acid uptake only minimally supports FAO in ovarian cancer cells that reside in the COL11A1-rich microenvironment." (PMID 32312965, 2020).
ovarian carcinoma (continued). "Although CD36 did not meet the criteria for all seven types of cancers studied, a high CD36 gene expression level was proposed as a poor prognostic marker in colon and ovarian cancer when assessed in panel with other proteins." (PMID 30069479, 2018). "Besides, elevated FAs imported via CD36 were also testified to accelerate tumors’ epithelial-mesenchymal transition (EMT), while inhibition of CD36 could impair the metastasis of human oral cancers and prevent the development of the adipocyte-induced malignant phenotypes in ovarian cancer." (PMID 36172157, 2022).
oral cancer (44 papers, 2018 to 2025). "In fact, enhanced presence of tumor cells expressing high levels of CD36 and increased metastatic potential is associated with a poor prognosis and clinical outcome in both glioblastoma and oral carcinoma." (PMID 35008415, 2022). "Particularly the differential cytotoxicity by H. parainfluenzae against the oral cancer cell lines and the downregulation of CD36 by the health-associated species, and the possibility of exploiting them for prevention or/and treatment of oral cancer, are worth further investigation." (PMID 33123499, 2020). "CD44+/CD36+ cells have been associated with invasion and metastasis in oral carcinoma." (PMID 31847105, 2019). "For example, a subset of CD44bright cells in an oral carcinoma model display high expression of the fatty acid translocase CD36 and rely on lipid uptake and β-oxidation for metastasis formation." (PMID 41404065, 2025). "More recently, we demonstrated that selective inhibition of CD36 can induce antitumor immunomodulatory effects in a mouse model of oral cancer." (PMID 41465497, 2025). "CD36 enhances the metastatic capability of cancer cells, particularly in the presence of a high‐fat diet, and neutralizing antibodies targeting CD36 have been shown to almost completely inhibit metastasis in orthotopic mouse models of human oral cancer." (PMID 40552664, 2025). "Overall, our data suggest that CD36 is indispensable in the proliferation and survival of oral cancer cells and regulates various immunological functions in oral tumor-bearing hosts." (PMID 39273384, 2024). "Using neutralizing antibodies for CD36 blockade, they were able to inhibit metastasis formation in orthotopic mouse models of human oral cancer." (PMID 38659591, 2024). "Further studies are necessary to elucidate an effective and safe clinical setting for CD36 inhibitors and to develop a more personalized medicine for oral cancer treatment." (PMID 39273384, 2024). "Compared to GLS, there are more studies focused on CD36 and tumor metastasis, so we validated this marker in oral cancer cell lines in vitro." (PMID 37207149, 2023). "The PCR results showed that expression levels of EMT markers and genes related to metastasis such as S100A8 and S100A9 were significantly decreased after knocking down CD36 in oral cancer cells." (PMID 37207149, 2023). "We knocked down CD36 in SCC9 and SCC25 cells and observed CD36 silencing significantly inhibited aggressive behaviors of oral cancer cells by transwell migration and invasion assay." (PMID 37207149, 2023). "Accordingly, targeting metastasis-initiating cells by an anti-CD36 antibody showed high efficacy in oral cancer mouse models of human oral carcinomas." (PMID 35406721, 2022). "Inversely, CD36 overexpression in human oral carcinoma cells with low metastatic potential drives macro-metastasis in lymph nodes without potentiating primary tumor size." (PMID 35945203, 2022). "The findings of recent studies showed that cancers with enhanced expression of CD36/SR-B2, induced by a high-fat diet or by palmitic acid in mouse models of human oral cancer, have a proclivity for metastasizing." (PMID 36012230, 2022). "In human oral carcinomas, a tumor cell population that initiates metastasis is characterized by increased expression of CD36 and lipid metabolism genes." (PMID 34983949, 2022). "It was reported that a subpopulation of oral carcinoma cells that express high levels of CD36 were unique in their ability to initiate metastasis in vivo." (PMID 35008415, 2022). "Lipid uptake via CD36 and the induction of β-oxidation boosts the metastatic potential of human oral carcinomas, which is inhibited by anti-CD36 antibody therapy in orthotopic mouse models of human oral cancer." (PMID 34983949, 2022). "CD44 + cells in slow-cycling human oral carcinomas express high levels of the fatty acid receptor CD36 and lipid metabolism genes to initiate metastasis." (PMID 35892853, 2022).
oral cancer (continued). "Within CD44bright human oral carcinoma cells, a subset of CD36+ (fatty acid receptor) cells respond to dietary lipids and increase metastatic initiation in LNs, while blocking CD36 ablates this phenotype." (PMID 33808959, 2021). "Human oral cancer metastasis initiating cells have been shown to express the surface protein CD36 that helps promote the metastasis of oral cancer through CD36‐mediated FAs uptake." (PMID 34766135, 2021). "In recent years, fatty acid receptor CD36 has been shown to play an essential role in the metastasis of oral cancer because CD36 is positively correlated with lymph node metastasis and can be used as a marker of metastasis initiating cells." (PMID 34977870, 2021). "CD36 antibody therapy has recently been shown to reduce cancer severity in preclinical models of human orthotopic oral cancer and prostate cancer patient-derived xenografts, supporting the clinical significance of antibody-based therapeutic targeting of CD36." (PMID 31022903, 2019). "Previous study has shown that a kind of cells expressing high level of the fatty acid receptor CD36 has been found in human oral cancer samples, and they have a high metastatic potential in mice." (PMID 31462892, 2019). "CD36 in its role as a cell surface receptor has been shown to promote the initiation and progression of oral carcinoma by mediating the uptake of exogenous fatty acids across the plasma membrane." (PMID 31655604, 2019). "In particular, these cells were found to have high expression of CD36 and were sufficient and necessary for metastasis in oral carcinoma." (PMID 31769430, 2019). "In oral carcinoma cell lines and patient samples, CD36+/CD44+ cells were slow-cycling, and, in accordance with transcriptome signatures representing lymph node metastasis, they also homed to lymph nodes in xenografts." (PMID 31661927, 2019). "Consequently, high CD36 expression was significantly correlated with high malignancy in oral cancer." (PMID 41465497, 2025). "We also examined whether co-culture with the CAL27 oral cancer cell line influenced CD18/CD36 expression in blood neutrophils from healthy donors." (PMID 40549016, 2025). "CD36 was shown to promote oral carcinoma migration and invasion in vitro and metastasis in vivo." (PMID 35008415, 2022). "Likewise, SR-B2/CD36+ human oral carcinoma cells initiate metastasis in an SR-B2/CD36-dependent manner, and SR-B2/CD36 antibody therapy inhibited metastasis in preclinical models." (PMID 33413672, 2021). "The blockage of CD36 could inhibit the metastasis of oral cancer and reduced the size of lymph node metastases." (PMID 34603046, 2021). "Studies done suggest CD36 may promote cell migration and proliferation in oral cancers and other solid tumors." (PMID 32954225, 2020). "Furthermore, the presence of CD36 positive metastasis initiating cells correlates with a poorer prognosis in glioblastoma and oral carcinoma." (PMID 32850342, 2020). "CD36+ oral carcinoma cells could initiate tumor metastasis more effectively than CD36− cells, while retaining the same ability to generate tumors at the primary site." (PMID 31769430, 2019). "Likewise, CD36-mediated FA uptake was found to promote metastatic development in a subpopulation of human oral carcinoma cells that express high levels of CD36." (PMID 29765537, 2018). "However, the correlation between CD36 expression and the clinicopathological characteristics of oral cancer remains unclear." (PMID 41465497, 2025). "Moreover, our present study revealed that CD36 inhibition attenuated the immune suppressive properties in OSCC-bearing hosts, suggesting that CD36 may be a potential biomarker for antitumour immune responses in oral cancer." (PMID 39273384, 2024).
oral cancer (continued). "A 2017 study showed that dietary lipids enhanced the ability of the CD36 subpopulation of oral carcinoma cells to metastasize and treatment with anti-CD36 neutralizing antibodies inhibited metastasis initiation and induced significant regression of established oral carcinoma metastases." (PMID 35008415, 2022). "Moreover, the use of CD36-neutralizing antibodies caused almost complete inhibition of metastasis in several mouse models of human oral cancer, with no side effects." (PMID 34063116, 2021). "Interestingly, some fatty acids (e.g., palmitic acid), or a high-fat diet, enhance the metastatic potential of cells in a CD36-dependent manner, whereas blocking CD36 causes inhibition of metastasis in mouse models of human oral cancer, with no side effects." (PMID 33718197, 2021). "Interestingly, in a previously published study in oral carcinoma, the effect of CD36 inhibition was associated with inhibition of metastasis, but not with growth of primary oral cancers." (PMID 32850342, 2020). "Neutrophils isolated from healthy donor blood were cultured with the oral cancer cell line CAL27 in vitro to investigate its impact on neutrophil lifespan and expression of CD18 and CD36." (PMID 40549016, 2025). "Our previous study demonstrated that CD36 plays a role in the proliferation and migration of oral squamous cell carcinoma (OSCC), suggesting its potential as a novel therapeutic target for oral cancer." (PMID 41465497, 2025). "Then, we validated the metastasis promoting characteristics of CD36 in vitro in two oral cancer cell lines: SCC9 and SCC25, both of which exhibit relatively high endogenous CD36 levels." (PMID 37207149, 2023). "Notably, at least in the context of oral carcinoma, palmitic acid or a high-fat diet specifically boosts metastatic potential of CD36+ metastasis-initiating cells in a CD36-dependent manner, suggesting that metastasis-initiating cells may rely on dietary lipids to promote metastasis." (PMID 32549336, 2020). "In addition, our in vitro experiments indicate that co-culture with an oral cancer cell line is not enough to induce the expression of CD36 in blood neutrophils from healthy donors." (PMID 40549016, 2025). "Additionally, they found that knockdown or inhibition of CD36 did not affect oral carcinoma primary xenograft tumor growth, but almost completely abolished local invasion." (PMID 35008415, 2022).
Hyperglycemia (41 papers, 2005 to 2025). An increased concentration of glucose in the blood. "Our data suggests that CD36 deficiency in Nrf2-deficient mice is a powerful antiatherogenic factor, which can override multiple pro-atherogenic conditions, which were present in the ApoE−/−Nrf2−/− mice, including oxidative stress, hypertriglyceridemia and hyperglycemia." (PMID 19023427, 2008). "Indeed, increased CD36 expression in PTECs in human DNP in vivo may be caused by hyperglycemia, as we show that high glucose concentration stimulates CD36 expression in vitro." (PMID 15737001, 2005). "For example, in atherosclerotic patients with hyperglycemia, there is an increase in post-translational modifications, specifically glycosylation, that contribute to higher functional CD36 levels." (PMID 41465460, 2025). "The effect of hyperglycemia on the expressions of CD36 and CD69 is supported by the significantly increased mRNA expression and protein expression of CD36 and CD69 in healed wounds in diabetic rats." (PMID 41465460, 2025). "Limitations of the study and future perspective: The study highlights the effects of hyperglycemia on the expression of CD36, CD69, CD274, and TLR-7 in rat tissues and rat fibroblasts." (PMID 41465460, 2025). "Early studies suggested that CD36 expression was more common in endarterectomy specimens from people with reported hyperglycemia." (PMID 37378396, 2023). "The lack of a detectable changes CD36 in response to the glucose challenge in LETO suggests that, during healthy conditions, CD36 protein levels are maintained despite the hyperglycemia." (PMID 34327606, 2022). "Similar to SRA, hyperglycemia increases CD36 mRNA abundance and translational efficiency, leading to more scavenger receptors expressed on the membrane." (PMID 35795646, 2022). "miR-320 is presumably upregulated in the heart by hyperglycaemia, which acts through CD36 (fatty acid translocase) transcription." (PMID 32276307, 2020). "In summary, CD36 mediates apoptosis of tubular cells induced by hyperglycemia, glycated albumin, FAs, or oxHDL, while hyperglycemia, albumin, AOPPs, or oxLDL promote interstitial fibrosis by EMT, the secretion of ECM proteins, and TGF-β1 and inflammation." (PMID 32796572, 2020). "CD36 participates in the pathogenesis of DR through a number of effects induced in retinal cells in response to hyperglycemia, FFAs, and modified lipoproteins." (PMID 32796572, 2020). "Our previous work has demonstrated that miR-320 is up-regulated in the heart by hyperglycaemia, which acts in the nucleus to enhance CD36 transcription and promote FA uptake, eventually leading to myocardial lipid deposition." (PMID 33186123, 2020). "Taken together, these data suggest that CD36 participates in hyperglycemia and oxLDL-induced osteoblastic differentiation of VSMC." (PMID 33028031, 2020). "The inhibition of CD36 reduces hyperglycemia-induced ROS production, activation of the ERK1/2 and Smad2 signaling pathway, and expression of prosclerotic cytokine TGF-β1 and ECM protein fibronectin." (PMID 32796572, 2020). "Hyperglycemia has been described as an important stimulator of in vitro CD36 expression, both on the mRNA and protein levels." (PMID 28729885, 2017). "This study aims to investigate the effects of hyperglycemia on the expression of various factors, including surface receptors CD36, Toll-like receptor (TLR)-7, programmed death-ligand 1 (PD-L1, also known as CD274), and CD69, in tissues from diabetic rats compared to control rats." (PMID 41465460, 2025). "Importantly, targeted silencing of Cd36 expression in liver macrophages improves glucose tolerance and ameliorates hyperglycemia in HFD‐fed mice, confirming the translational implication of CD36." (PMID 41163804, 2025). "The change in the expression of CD36 with hyperglycemia may be due to regulation at the post-transcriptional and post-translational levels." (PMID 41465460, 2025). "Hyperglycemia is considered an important stimulator of CD36 mRNA synthesis in vitro." (PMID 36613720, 2022).